STAT3 (signal transducer and activator of transcription 3)
Diseases named in the same sentence as STAT3 in open-access papers (continued):
Sharing a sentence is not in itself a finding about the gene and the disease.
endometriosis (42 papers, 2015 to 2026). The growth of functional endometrial tissue in anatomic sites outside the uterine body. "Persistent activation of STAT3 by IL6ST signaling has been associated with development of fibrosis in endometriosis." (PMID 39821173, 2025). "Activated STAT3 and NFκB signaling by cytokines and chemokines associated with immune cells have been shown in endometriosis." (PMID 35203298, 2022). "A proinflammatory cytokine IL-6 is elevated in the peritoneal fluid and serum of women with endometriosis and induces prolonged activation of STAT3 via association with the IL-6 receptor to enhance endometriosis progression." (PMID 36358904, 2022). "Thus, while loss of STAT3 compromises uterine function, aberrant activation is associated with endometriosis, indicating the need for tight regulation of STAT3 in conjunction with PGR signaling." (PMID 31387263, 2019). "This study highlights YWHAZ as a potential molecular node connecting progesterone resistance and STAT3 dysregulation to defective endometrial function and infertility in endometriosis." (PMID 41885596, 2026). "Our results suggest an interplay between complement and coagulation, mast cells, extracellular matrix remodeling, and the JAK/STAT3 pathway in endometriosis." (PMID 40698088, 2025). "Others have shown that phosphorylation of STAT3 was upregulated in endometriosis lesions and activated STAT3 increased proliferation of endometrial stromal cells." (PMID 40698088, 2025). "The miR-320 family, similarly, implicated in endometriosis, has shown involvement in cell proliferation and invasion, acting through pathways such as PI3K/Akt and STAT3." (PMID 40429709, 2025). "Recent studies show that sustained STAT3 activation promotes endometriosis fibrosis by enhancing IL-10 and IL-6 anti-inflammatory effects." (PMID 41170181, 2025). "Our results present a similar picture; complement C3 as well as the JAK/STAT3 pathway seems to play a role in the development of endometriosis." (PMID 40698088, 2025). "For example, increased levels of the cytokine interleukin-6 (IL-6) have been reported in the serum of patients with endometriosis, leading to persistent activation of the signal transducer and activator of transcription 3 (STAT3) protein." (PMID 40422245, 2025). "Phosphorylation of STAT3 was upregulated in endometriosis lesions and activated STAT3 increased proliferation of endometrial stromal cells." (PMID 40948761, 2025). "Upregulation of JAK2(Janus kinase 2)/signal transducer and activator of transcription 3 pathway has also been observed in endometriosis." (PMID 39821173, 2025). "The role of STAT3 during the development of endometriosis is unclear, but studies have shown high levels of phosphorylated STAT3 (pSTAT3) in the endometrium of women with endometriosis compared to controls." (PMID 39201680, 2024). "The production of CTGF, a key marker in fibrotic disorders such as endometriosis and intrauterine adhesions, is through STAT3-dependent Smad signaling." (PMID 39201680, 2024). "IL-6/soluble IL-6 receptor (sIL-6R) signaling dysfunction leads to the persistent activation of STAT3 and NF-κB, which induces the collagen synthesis of ESCs, contributing to the fibrosis of endometriosis." (PMID 36865552, 2023). "B Cell lymphoma 6 (BCL6), a transcriptional gene repressor and a target of STAT3, has been shown to be upregulated in endometriosis." (PMID 37108154, 2023). "The overexpression of BCL6 appears to result from the phosphorylation of STAT3 in the eutopic endometrium of women with endometriosis." (PMID 37108154, 2023). "In endometriosis, we also found that niclosamide reduced the growth of lesions and decreased inflammation at lesion sites through its suppression of STAT3 and NF-κB signalling." (PMID 36369244, 2022).
endometriosis (continued). "In a murine endometriosis model, established by surgically inducing endometriotic‐like lesions, niclosamide (100 and 200 mg·kg−1, p.o.)decreased the growth rate and progression of endometriosis‐like lesions and inhibited STAT3 and NF‐κB pathways." (PMID 35348204, 2022). "One effect of STAT3 overexpression in endometriosis appears to be the up-regulation of the oncogenic gene repressor B cell CLL/lymphoma 6 (BCL6), a known target of STAT3 and shown to be increased in the secretory phase endometrium of women with endometriosis." (PMID 31387263, 2019). "One potential mechanism suggested for increased STAT3 activation in endometriosis is down-regulation of protein inhibitor of activated STAT3 (PIAS3) which has been observed in women and non-human primates with endometriosis." (PMID 31387263, 2019). "Taken together, our findings suggest that CUR has therapeutic potential to abrogate aberrant activation of chemokines and cytokines, and IKKα/β, NF‐κB, STAT3, and JNK signaling pathways to reduce inflammation associated with endometriosis." (PMID 30259980, 2019). "IL-6 mediated activation of STAT3 was correlated with fibrosis in endometriosis." (PMID 40948761, 2025). "Furthermore, IL6ST facilitated progression of endometriosis by activating mitogen-activated protein kinase 9/Signal Transducer and Activator of Transcription 3 signaling pathway." (PMID 39821173, 2025). "Several studies have shown elevated levels of IL-6 in peritoneal fluid of patients with endometriosis, which led us to investigate whether the expression of miR-21, via STAT3, is induced by IL-6." (PMID 39201680, 2024). "In addition, our findings align with other recent studies that showed that a persistent activation of STAT3 via IL-6 signaling is involved in fibrosis in endometriosis." (PMID 39201680, 2024). "In this study, we hypothesized that the inflammatory environment, specifically IL-6, in the peritoneal cavity of women with endometriosis could upregulate miR-21 via STAT3, leading to an increase in fibrosis in endometriosis." (PMID 39201680, 2024). "Moreover, they also suggested that the estrogen-autophagy-STAT3-HCK-NK cell axis participates in the pathogenesis of endometriosis." (PMID 36865552, 2023). "In addition, NCL decreased the growth rate and progression of endometriosis-like lesions and inhibited STAT3 and NF-κB pathways." (PMID 37242480, 2023). "Moreover, the dysregulation of the IL6/STAT3 signaling pathway in endometriosis can also be induced under hypoxia conditions and in the presence of inflammatory cytokines such as TNFA, contributing to the establishment of ectopic tissue." (PMID 36232817, 2022). "Inflammation-related pathways such as IL6-JAK/STAT3 signaling, inflammatory response, interferon α response, interferon γ response, and TNFα signaling via NF-κB, were found to be significantly upregulated in patients with endometriosis." (PMID 36339397, 2022). "STAT3 was found to be targeted by both miR-2861 and miR-424-5p, and their downregulation could inhibit apoptosis in endometriosis." (PMID 36143357, 2022). "PI3K/Akt and STAT3 pathways are also involved in the pathogenesis of endometriosis." (PMID 32076458, 2020). "In conclusion, 17β-estradiol and TCDD in the ectopic milieu may lead to the development of endometriosis by inducing M2 polarization of macrophages through activation of the STAT3 and P38MAPK pathways." (PMID 25950905, 2015). "Given its interaction with PGR during early pregnancy establishment, one might have hypothesized STAT3 activation would be reduced in endometriosis due to the context of P4 resistance, however pSTAT3 is aberrantly increased in the endometrium of both women and non-human primates with endometriosis." (PMID 31387263, 2019). "In stark contrast, FMT from endometriosis patients exacerbates disease progression by impairing microbial ecology, diminishing acetate production, failing to activate JAK1/STAT3, promoting M2 polarisation and disrupting gut barrier function." (PMID 40739711, 2025).
endometriosis (continued). "We highlight the role of complement and coagulation cascade in endometriosis and propose an interplay between both those processes and mast cells, ECM interaction, and the JAK/STAT3 pathway that needs further investigation." (PMID 40698088, 2025). "In support of PIAS3 having an active role in preventing endometriosis, an in vitro study has shown that INFγ can reduce PIAS3 but increases p-STAT3, suggesting aberrant STAT3 activation by attenuation of PIAS3." (PMID 35203298, 2022). "However, in endometriosis development, the effect of STAT3 on DCs maturation remains unclear." (PMID 34429116, 2021). "In summary, our findings reveal that Activin A induces myofibroblast differentiation of endometrial MSCs via STAT3-dependent Smad/CTGF pathway and that blocking Activin A signal ameliorates fibrosis in endometriosis." (PMID 31101053, 2019). "In turn, reduced expression of GLI1 was shown in the endometrium of women with endometriosis, confirming a mechanistic role for STAT3, BCL6, and SIRT1 overexpression in the P4 resistance of endometriosis." (PMID 31387263, 2019). "To date, no gain-of-function mutations in JAK1, STAT3, STAT5B, or STAT6 have been identified in human endometriosis tissues, cell lines, or animal models." (PMID 40948761, 2025). "Tofacitinib effectively reduced STAT3 phosphorylation in Ishikawa cells and in human primary stromal and epithelial cells in patients with or without endometriosis." (PMID 36532015, 2022). "The global expression profile enriched critical pathways already related to the endometriosis condition, such as PI3K signaling via AKT to mTORC1, mTORC1 signaling, TNFA signaling via NFkB, IL6 STAT3 signaling, TGF beta signaling, and hypoxia via HIF1A targets." (PMID 36232817, 2022). "In addition, the levels of activated STAT3 (PIAS3) protein inhibitor, which negatively regulates STAT3 activity, were significantly lowered in women with endometriosis." (PMID 36358904, 2022). "The levels of activated STAT3 were significantly elevated in proliferative and secretory phase endometriotic tissues from women with endometriosis compared with tissues from women without the disease." (PMID 36358904, 2022). "Although STAT3 directly interacts with the PRA isoform and is required for normal endometrial functions such as decidualization, STAT3 constitutive stimulation is activated by inflammatory factors from tissue residential or peritoneal immune cells in endometriosis." (PMID 35203298, 2022). "In addition to its aid in the survival of the endometriosis cells, an investigation conducted to examine the relationship between EPHA3 and the expression of signaling proteins flagged the suppression of several signaling proteins, including PI3K, STAT3 and BMX as a result of EPHA3 overexpression." (PMID 31262977, 2019). "However, it is not clearly described whether STAT3 regulates STAT1 in endometriosis yet." (PMID 36358904, 2022). "Aberrant p-STAT3, co-occurring with HIF1A, presents in the eutopic endometrium in humans and non-human primates with endometriosis." (PMID 35203298, 2022).
pulmonary hypertension (42 papers, 2009 to 2026). Increased pressure within the pulmonary circulation due to lung or heart disorder. "The STAT family, and STAT3 in particular, are broadly implicated in the pathogenesis of pulmonary hypertension in animal as well as human tissue models." (PMID 30081463, 2018). "Basic research has confirmed the involvement of STAT1 and STAT3 in the pathogenesis of pulmonary arterial hypertension, with STAT1 activation being closely associated with a pro-inflammatory phenotype, whereas STAT3 promotes cell survival and inhibits apoptosis." (PMID 40332339, 2025). "IL‐6 signals via STAT3 and knowing that STAT3 signaling is linked to both pulmonary hypertension and inflammation, we studied whether total STAT3 and Tyr705 phosphorylation were increased in the investigated organs during hypoxia." (PMID 39034131, 2024). "MiR-204 inhibits the Src family kinases (SRC)/Signal Transducer and Activator of Transcription 3 (Stat3) module, regulating pulmonary hypertension." (PMID 40565979, 2025). "Previous studies have shown that STAT3 is involved in various types of pathological vascular changes, including vascular remodeling, vascular calcification, and pulmonary arterial hypertension." (PMID 40607212, 2025). "In this study of hypoxic pulmonary hypertension, epithelial derived IL‐18 can be a trigger of pulmonary inflammation and pulmonary hypertension via IL‐6 generation in infiltrating monocytes/macrophages and STAT3 signaling." (PMID 39034131, 2024). "The aberrant glycolytic processes in response to hypoxia mediate the effect of JMJD1C on the development of pulmonary hypertension by activating STAT3 signaling." (PMID 36934091, 2023). "EV inhibited the hypoxic activation of STAT3 signaling and upregulation of miR-204 and miR-17 in a mouse model of suppressed pulmonary hypertension." (PMID 36875046, 2023). "MEX downregulated the expression of miR-17 which is regulated by STAT3 suggesting that MEX is a key modulator of hyperproliferative signaling by inhibition of STAT3 in hypoxia-induced pulmonary hypertension." (PMID 34869682, 2021). "The same investigators also showed that hormone–responsive pulmonary hypertension requires a functional STAT3 signaling axis." (PMID 30081463, 2018). "Remarkably, as determined in a rat model of chemically-induced pulmonary hypertension, similar increases in tyrosine phosphorylated STAT3, and the expression levels of cyclin D1 and D3 were observed in whole lung homogenates from Cav-1 and Cav- 2 KO mice." (PMID 26605130, 2012). "Interestingly, the levels of tyrosine 705-phosphorylated STAT3 (PY-STAT3) are increased in the lungs of rats with pulmonary hypertension induced by hypobaric hypoxia." (PMID 34434114, 2021). "These therapies may prove to be especially helpful in combination with other drugs that target the STAT3 pathway shown to have efficacy in pulmonary hypertension management, such as dehydroepiandrosterone (DHEA)." (PMID 30081463, 2018). "Furthermore, and contrary to the lysosomal localization of STAT3 induced by pulmonary arterial hypertension, STAT3 resided on the cytosolic side of the lysosomal membrane in normally growing cancer cells." (PMID 30127373, 2018). "In mouse hypoxic pulmonary hypertension model, intravenous delivery of MSC-derived exosomes inhibited vascular remodeling and alleviated pulmonary hypertension through the suppression of signal transducer and activator of transcription 3 (STAT3) and the upregulation of the miR-17 superfamily." (PMID 28147325, 2017). "STAT3 was originally identified as an acute-phase response factor activated by many cytokines, with an important role in the development of cardiovascular diseases, including pulmonary arterial hypertension (PAH)." (PMID 29179437, 2017).
pulmonary hypertension (continued). "For instance, MSC-EVs mediate cytoprotective actions in a model of pulmonary hypertension by suppressing hyperproliferative pathways such as the signal transducer and activator of transcription 3 (STAT3) pathway as well as upregulating miRNAs that are downregulated during pulmonary hypertension." (PMID 26649044, 2016). "In pulmonary hypertension an auto-regulatory positive feedback has been reported, in which STAT3 activation might perpetuate miR-204 downregulation." (PMID 27457246, 2016). "Importantly, delivery of a cell permeable peptide containing CSD reversed pulmonary hypertension and the accompanying increases in pulmonary phospho-STAT3, cyclin D1, and cyclin D3 expression in rats exposed to monocrotaline." (PMID 26605130, 2012). "Interestingly, in addition to rats with chemically-induced pulmonary hypertension, a similar increase in tyrosine phosphorylated STAT3, and the expression levels of cyclin D1 and D3 were observed in whole lung homogenates from Cav-1 KO mice." (PMID 26605130, 2012). "In addition, VGLL4 promotes pulmonary hypertension and pulmonary arterial remodeling through a signal transducer and the activation of transcription 3 (STAT3) signaling; alternatively, the specific knockout of VGLL4 in ECs increases the YAP expression and heart valve malformation." (PMID 36675179, 2023). "Finally, there are a number of ways that identified MDSC and T cell populations may contribute to pulmonary hypertension through many of the previously discussed metabolic or signaling pathways, including Arg1, iNOS, STAT3, and PD-L1/2 activation." (PMID 30081463, 2018). "In mice with hypoxia-induced pulmonary hypertension, MSC-EVs induced anti-inflammation by inhibiting signal transducer and activator of transcription 3 (STAT3) signaling." (PMID 36117725, 2022). "Moreover, in a mouse model of hypoxia-induced pulmonary hypertension, MSC-derived EVs exerted therapeutic effects by suppressing inflammation through the inhibition of the signal transducer and activator of transcription 3 (STAT3) pathway in the lung." (PMID 35742923, 2022). "The miR-130/301 family expression levels are increased in pulmonary hypertension, resulting in a decrease in miR-204, miR-322 and miR-503 via peroxisome proliferator-activated receptor gamma (PPARG) and signal transducer and activator of transcription 3 (STAT3)." (PMID 33973623, 2021).